AR (androgen receptor)
Diseases named in the same sentence as AR in open-access papers (continued):
Sharing a sentence is not in itself a finding about the gene and the disease.
prostate carcinoma (continued). "AR modulates cellular proliferation and metastasis in androgen-dependent and -independent prostate cancer cells, and hence, is a major drug target to manage the disease." (PMID 37190127, 2023). "There is growing yet insufficient evidence regarding androgen receptor–independent mechanisms for progression of prostate cancer, including the impact on nutrition, genomics, and inflammation." (PMID 38033743, 2023). "Results here would confirm recent evidence suggesting that PPARγ is generally associated with a poor prognosis in prostate cancer, since it is related to an increase in AKT expression and further mitogenesis or other AR-dependent and independent mechanisms." (PMID 37770940, 2023). "The aberrant activation of AR is a primary driver of prostate cancer progression; hence, AR is a primary therapeutic target for this disease." (PMID 36980655, 2023). "Lysine-specific demethylase 1 (KDM1A/LSD1) removes the mono- and di-methylation from H3K4 and H3K9, and plays an important role in regulating AR-dependent gene expression in prostate cancer." (PMID 36776288, 2023). "Sgk1 has been established as a gene upregulated by AR activation in both healthy and prostate cancer cells." (PMID 38303978, 2023). "Since this first demonstration, melatonin-mediated nuclear exclusion of the AR in prostate cancer cells has been demonstrated repeatedly, corroborating the indolamine’s anti-androgen effect on prostate cancer cells." (PMID 37191417, 2023). "Androgen deprivation therapy (ADT), the first line of treatment for progressive prostate cancer, is effective at first but eventually fails due to the development of resistance, primarily through androgen-independent reactivation of AR." (PMID 37563360, 2023). "The function and expression pattern of HSD17B2 is reported to reduce prostate cancer, as it suppresses AR signaling and cell growth by blocking androgen synthesis." (PMID 37858151, 2023). "Prostate cancer cells can increase de novo lipogenesis and fatty acid oxidation by up-regulating androgen receptor (AR)-regulated lipogenic enzymes." (PMID 36824662, 2023). "When initially diagnosed, the vast majority of metastatic prostate cancers exhibit a phenotype consistent with a secretory luminal cell that is regulated by androgens through the androgen receptor (AR) signaling program." (PMID 37823778, 2023). "Another study using the AR-positive LNCaP and the AR-negative PC-3 prostate cancer cell lines showed that compound 1 was antiproliferative and pro-apoptotic in both cell lines, albeit the pro-apoptotic effects were higher in the AR-positive cells." (PMID 36835501, 2023). "Here, we report a central role for Sigma1 in the interplay between AR signaling, autophagy, LDs, and the maintenance of oncogenic ROS levels in prostate cancer cells." (PMID 37874216, 2023). "Gene expression changes found in prostate cancer can be understood through their effects on AR signaling." (PMID 36937425, 2023). "Recent data have shown that ETS translocation alters the chromatin enhancer landscape and the AR cistrome in prostate cancer." (PMID 37018402, 2023). "In prostate cancer cells, UA downregulates RORγ-stimulated AR expression and AR signaling, whereas digoxin upregulates AR signaling pathway." (PMID 37180705, 2023). "PSA has been reported to promote the growth of AR-positive hormone-refractory prostate cancer cells such as CWR22rv1 and high passage LNCaP10." (PMID 37794090, 2023). "The reduced pAkt in turn downregulates AR Ser213 phosphorylation, thereby enhancing AR stability and transcriptional activity, promoting the development of prostate cancer." (PMID 37752518, 2023). "In turn, Pt(IV) conjugate 85, composed of an AR-binding nonsteroidal cyanonilutamide unit, 7-hydroxycoumarin, and cisplatin moiety, represents the AR antagonist intended for castration-resistant prostate cancer treatment." (PMID 38139858, 2023).
prostate carcinoma (continued). "Androgen receptor (AR) is the most critical determinant of the occurrence, progression, metastasis, and treatment of prostate cancer." (PMID 37326412, 2023). "Although the androgen receptor (AR) is the most important treatment target for prostate cancer, with the widespread use of Enzalutamide, an increasing number of patients receiving androgen deprivation treatment (ADT) have progressed to the CRPC stage." (PMID 37095108, 2023). "Apalutamide, a high-affinity AR inhibitor, binds directly to the ligand-binding domain of AR and inhibits nuclear localization and DNA binding within prostate cancer cells." (PMID 37342589, 2023). "Propofol decreases androgen receptor activation as well as decreases the occurrence of castration-resistant prostate cancer." (PMID 37297021, 2023). "The current approved therapies for advanced, metastatic castration-resistant prostate cancer include androgen-receptor axis-targeted agents, taxane chemotherapy, radium-223, and sipuleucel-T." (PMID 36674745, 2023). "Large interest in the degradation of the androgen receptor (AR) as a new anti-prostatic cancer strategy has resulted in several papers focusing on PROTACs against AR." (PMID 36770875, 2023). "Hormone therapy plays an important role in the treatment strategy of prostate cancer patients, and the new generation of AR pathway inhibitors provide more options to treat patients with advanced prostate cancer." (PMID 36925917, 2023). "For example, PROTAC ARV-110, which uses UPP to degrade the androgen receptor (AR) protein, has demonstrated some efficacy in the treatment of prostate cancer, especially metastatic castration-resistant prostate cancer (mCRPC)." (PMID 36969062, 2023). "In this review, we summarize the regulation and role of ferroptosis in prostate cancer and the relationship with AR from the perspective of metabolism and molecular pathways." (PMID 37061523, 2023). "The action of SMILE on the androgen receptor (AR), a key receptor in prostate cancer regulation, is important in the transactivation of androgenic genes." (PMID 36769229, 2023). "Prevention of AR activity halts the disease progression, and prostate cancer is successfully treated with androgen-deprivation therapy." (PMID 36401094, 2023). "AR is a key transcription factor playing a critical role in prostate cancer initiation and progression." (PMID 36937425, 2023). "This study aimed to review the roles of p300 and TMPRSS2 (transmembrane protease, serine 2) in the AR (androgen receptor) pathway as they are closely related to the development and progression of prostate cancer." (PMID 37511059, 2023). "A novel AR splice variant, AR8, was found to be localized to the plasma membrane via palmitoylation at Cys588 and Cys560, and overexpression of AR8 reduced prostate cancer cell proliferation and enhanced apoptosis in androgen‐depleted culture conditions." (PMID 36018061, 2023). "Decreasing zinc level, e.g., during propagation of prostate cancer, would destabilize the AR’s transcriptional complexes." (PMID 37686614, 2023). "Studies have revealed that the AR can regulate the progression of prostate cancer cells by activating other receptors." (PMID 37681860, 2023). "The importance of both PKA and cAMP in the development of prostate cancer, and their interactions with the androgen receptor, were the focus of a review by Merkle and Hoffmann in 2010." (PMID 37830741, 2023). "Prostate cancer develops in the prostate gland mainly due to dysregulated androgen signaling through the androgen receptor." (PMID 37104249, 2023). "LDs in prostate cancer cells have been reported to be induced by both AR-dependent and -independent mechanisms." (PMID 37874216, 2023). "While AR-mediated activation of RUNX1 has previously been reported in prostate cancer cells, evidence for the AR directly binding to the RUNX1 promoter/gene body is limited in that context and has not been demonstrated in breast cancer." (PMID 36766786, 2023).
prostate carcinoma (continued). "KDM4A acts as a cofactor of the androgen receptor (AR) and stimulates AR-dependent transcription of proliferative genes via its demethylase activity on H3K9me3 in prostate cancer." (PMID 37553362, 2023). "The second drug, FT-7051, is an oral, potent, and selective inhibitor of p300/CBP with activity in preclinical models of prostate cancer, including models which are resistant to the currently used AR inhibitors such as enzalutamide." (PMID 37511059, 2023). "For example, androgen-responsive elements can upregulate the enzyme 3β-hydroxysterol Δ24-reductase (DHCR24) in AR-positive prostate cancer cells, thereby promoting cholesterol accumulation." (PMID 37312170, 2023). "In the process of castration resistance, we found that androgen receptor-mediated signals were lost in prostate cancer cells cultured under androgen-deprivation conditions, and GAG chain-mediated proliferation signals became dominant instead." (PMID 36511224, 2023). "The androgen receptor (AR) plays a key role in the progression of prostate cancer, and androgen-deprivation therapy (ADT) is the first line of treatment against advanced metastatic prostate cancer after surgery of the primary site." (PMID 36672395, 2023). "The LNCaP-PSA luciferase assay has been developed by transfecting a PSA promoter-firefly luciferase plasmid into LNCaP, an AR-positive prostate cancer cell line." (PMID 36765659, 2023). "We identified an imidazopyridine X15695 that potently inhibited proliferation of ER+ breast and AR+ prostate cancer cells." (PMID 37520743, 2023). "The general findings included lower AR expression and function, as well as the suppression of prostate cancer development." (PMID 38004496, 2023). "Alternatively, following RT there is an overexpression and over-activation of the Androgen Receptor (AR) in prostate cancer cells." (PMID 37444473, 2023). "(10R,11R) Derivatives 8A and 41A cannot suppress 22Rv1 prostate cancer cell proliferation up to 10 μM concentration, suggesting that they are very likely binding to the ligand-binding domain on AR to exhibit antiproliferative activity in LNCaP cells." (PMID 37111288, 2023). "In this review, we summarize the data that underlie the integration of chemotherapy into the management of advanced prostate cancer, including data supporting the combination of chemotherapy with next generation androgen receptor signaling inhibitors." (PMID 37568784, 2023). "Recent studies on two different mouse models, namely, the Hi-Myc genetic model and the T + E2 hormonal carcinogenesis model, demonstrate that stromal AR normally inhibits prostate cancer progression by restraining secretory luminal cells." (PMID 36891053, 2023). "Different steroid hormones have a key role in the maintenance and progression of prostate cancer, and their effects are achieved through the androgen receptor." (PMID 36671530, 2023). "As with ER in breast cancer, androgen receptor (AR) is integral to the development and progression of prostate cancer." (PMID 37265348, 2023). "PPARγ has been shown to support prostate cancer growth through its roles in fatty acid synthesis, mitochondrial biogenesis, and co-operating with androgen receptor signalling." (PMID 36510001, 2023). "These RBPs include e.g. FUS which interacts with AR,34, 35, 36 a key transcription factor driving prostate cancer." (PMID 37591798, 2023). "Aberrant AR signaling drives multiple aspects of prostate cancer cell metabolism, growth, proliferation, and cellular plasticity." (PMID 37874216, 2023). "In conclusion, our data illustrate the synergistic importance of AR antagonism and degradation in advanced prostate cancer treatment." (PMID 36656639, 2023). "With phase 1 testing complete, proxalutamide was positioned to be tested in the setting of COVID-19, along with other AR-targeted drugs that have been FDA-approved for prostate cancer for years, such as enzalutamide." (PMID 37459541, 2023).
prostate carcinoma (continued). "Knockdown of hnRNPA1 re-sensitized enzalutamide-resistant prostate cancer cells by inhibiting the splicing of androgen receptors (AR) and thereby reducing the expression of AR-V7." (PMID 36982162, 2023). "AR is acetylated, and its stability is regulated by p300, which promotes prostate cancer cell proliferation." (PMID 36979352, 2023). "Androgen receptor (AR)-targeted therapies such as enzalutamide have achieved considerable clinical success in patients with prostate cancer, mainly by attacking the glandular luminal cells." (PMID 37208335, 2023). "When combined with conventional androgen receptor inhibitors, AS-10 showed synergistic effects in prostate cancer treatment." (PMID 37765058, 2023). "Ferroptosis-mediating factors (SLC7A11, SLC3A2, GPX4) are aberrantly expressed in AR-resistant prostate cancer." (PMID 36744249, 2023). "Studies with AR antagonists prescribed for prostate cancer treatment (e.g., enzalutamide, apalutamide, and darolutamide) have since shown that SARS-CoV-2 infectivity can be decreased in vitro in certain contexts with these drugs (36, –38)." (PMID 37459541, 2023). "Given that ferroptosis-sensitive PC3 and DU145 cell lines also lack expression of the AR, a major driver of prostate cancer progression, we examined the regulation of ferroptosis by AR signaling." (PMID 36928314, 2023). "Prostate cancer is critically reliant on androgen receptor (AR) signaling and thus the suppression of gonadal androgen production through surgical or chemical castration (androgen deprivation therapy) has been a mainstay of treatment for advanced disease." (PMID 37041154, 2023). "The pivotal role of androgen signaling in prostate cancer progression has long been recognized, and suppression of androgen receptor-mediated effects on prostate cancer remains a pillar of its clinical management." (PMID 38104131, 2023). "The androgen receptor (AR) is an established orchestrator of cell metabolism in prostate cancer (PCa), notably by inducing an oxidative mitochondrial program." (PMID 37086156, 2023). "Celastrol was next examined in LNCaP prostate cancer cells that were positive for androgen receptor (AR) and shown to inhibit the proteasome and reduce the levels of AR." (PMID 37110167, 2023). "Studies have reported that metformin induces SMILE, which acts as a corepressor of AR and inhibits the proliferation of prostate cancer cells via androgen-dependent growth." (PMID 36769229, 2023). "The heterogeneity of androgen receptor (AR) gene alterations across metastases in prostate cancer remains unresolved." (PMID 37563129, 2023). "Regarding prostate cancer, the crosstalk between AR and EGFR signaling has been discussed from different viewpoints depending on the cell lines and culture conditions." (PMID 37463954, 2023). "Studies show the main leucine transporters are different in different stages of prostate cancer, especially in the castration-resistant stage of androgen receptor (AR) expression." (PMID 37047148, 2023). "Prostate cancer develops when the binding of androgens to the androgen receptor (AR) triggers a key specific oncogenic transcriptional program." (PMID 36967752, 2023). "AR NTD that governs the transcriptional activities of all active variants has been considered attractive therapeutic target to block AR signaling in prostate cancer cells." (PMID 36893587, 2023). "Other prostate cancer research points to aberrant activation of signaling pathways, such as androgen receptor (AR), epidermal growth factor receptor (EGFR), and inflammation, across races as potential causes of racial difference in incidence and mortality." (PMID 37345032, 2023). "During the transition from mHSPC to mCRPC, there are numerous escape mechanisms that prostate cancer cells can develop to circumvent androgen or AR dependence." (PMID 37810962, 2023).
prostate carcinoma (continued). "In the past few years, the US Food and Drug Administration has approved three second-generation androgen receptor inhibitors (SGARIs), namely enzalutamide, apalutamide, and darolutamide, to treat prostate cancer." (PMID 36967752, 2023). "Due to these discoveries, the first oral AR PROTAC degrader for prostate cancer was created, and despite anticipated pharmacokinetic difficulties such as poor cell permeability and limited bioavailability, it has shown promise in clinical testing." (PMID 37241755, 2023). "The limited availability of human prostate cancer cell lines that harbor both intact AR expression and androgen dependency have slowed prostate cancer research." (PMID 36806727, 2023). "The reduction in androgen synthesis and the blockade of the androgen receptor (AR) function by chemical castration and AR signaling inhibitors represent the main treatment lines for the initial stages of prostate cancer." (PMID 36768610, 2023). "Our data suggests the presence of a double-negative feedback loop between MALAT1 and PARP1 in both AR-negative and AR-positive prostate cancer cell lines." (PMID 37812088, 2023). "Overexpression is connected to castrate-resistant prostate cancers (CRPC), in which a sustained AR signal is considered the primary cause of CRPC." (PMID 36834602, 2023). "These miRNAs have also been shown to negatively regulate the expression of the androgen receptor in prostate cancer cells." (PMID 37190259, 2023). "The androgen receptor (AR), a member of the nuclear receptor superfamily, is a strong driver of proliferation in prostate cancer." (PMID 37936981, 2023). "So, there is an unmet need for drugs that can target the DNA repair pathways in IR-induced damaged DNA to radiosensitize prostate cancer cells in AR independent manner." (PMID 36959798, 2023). "This review will provide an updated snapshot on cAMP/PKA signalling in prostate cancer, including that relating to cross-talk with the AR signalling pathway." (PMID 37830741, 2023). "In fact, ARLNC1 has a role in the preservation of a positive feedback loop that induces AR signaling in the course of prostate cancer progression." (PMID 37025585, 2023). "Cellular levels of ROS and ROS-induced DNA double-strand break damage were analyzed in the absence and presence of AR signaling upon treatment of prostate cancer cells by either oxidants or inflammatory microenvironment exposure." (PMID 38155939, 2023). "Androgens such as testosterone and dihydrotestosterone activate AR signaling to promote the proliferation of prostate cancer cells." (PMID 37463954, 2023). "The aminosteroid derivative RM-581 blocks with high potency the growth of androgen-dependent (AR+) prostate cancer VCaP, 22Rv1, and LAPC-4 cells." (PMID 37296995, 2023). "The LNCaP prostate cancer cell line is the most widely used AR-positive cell line due to its significant expression levels of AR and the fact that it is an ER-negative cell line." (PMID 36835012, 2023). "The development of prostate cancer is mediated by abnormalities in AR signaling, and androgen deprivation therapy (ADT) is the cornerstone of systemic treatment for individuals with advanced PC." (PMID 37175108, 2023). "PPARγ can also interfere with prostate cancer cell growth by regulating androgen receptor (AR) levels and activity." (PMID 36902342, 2023). "Androgen receptor (AR) is the principal molecule in prostate cancer etiology and therapy and its re-activation remains a major challenge during treatment of prostate tumors that relapse after castration therapies." (PMID 37311884, 2023). "Around 80–90% of prostate cancers are androgen-dependent in their early stages, and for this reason, the main therapy consists of androgen receptor inhibition." (PMID 36677878, 2023). "Levels of TIF2 and SRC1 expression have been observed to rise alongside the expression of the AR during the progression of prostate cancer cells following androgen deprivation." (PMID 37894414, 2023).